INS (insulin)
Diseases named in the same sentence as INS in open-access papers (continued):
Sharing a sentence is not in itself a finding about the gene and the disease.
diabetes (continued). "Diabetes mellitus (DM) is a chronic disease, characterized by hyperglycemia, due either to impairment of insulin sensitivity, insulin secretion or both." (PMID 33071792, 2020). "Diabetes is typically treated with oral ­antidiabetic medicines, such as sulfonylureas and thiazolidine, as well as insulin injection." (PMID 33281368, 2020). "Diabetes is a metabolic disease characterized by hyperglycaemia due to the defect of insulin secretion or impaired insulin biological effect." (PMID 32281722, 2020). "This predictive value can be used to identify patients that can be targeted with more diabetes education and better insulin regimen for their glucose management at discharge." (PMID 33426086, 2020). "Diabetes mellitus (DM) is a chronic metabolic disease characterized by hyperglycemia, resulting from defects in insulin secretion, insulin action, or both." (PMID 33679605, 2020). "The diabetes stage that follows reflects failure / insufficiency of beta cells to compensate for the prevailing peripheral resistance to insulin, resulting in progressive hyperglycemia." (PMID 32128655, 2020). "Animal experiments have shown that estrogens can promote insulin secretion, reduce insulin resistance, and have a protective effect on diabetes." (PMID 32256451, 2020). "In diabetes, the use of nutraceuticals contributes to improve insulin sensitivity, metabolism regulation and lower hyperglycemia." (PMID 33081260, 2020). "Elevated levels of 3-hydroxybutyric acid are a clinical marker of ketoacidosis and disturbed insulin sensitivity in fasted and diabetic patients." (PMID 33302528, 2020). "Type 2 diabetes mellitus (T2DM) is a heterogeneous condition that is characterized by a gradual decrease in insulin action, accompanied by beta cells’ incapacity to compensate for insulin resistance." (PMID 33375437, 2020). "New cell-based therapy using MSCs for diabetes mellitus is anticipated as an alternative treatment option to insulin injection or islet transplantation in both human and veterinary medicine." (PMID 33133196, 2020). "Previous studies explained the effects of dietary fiber intake and the lowering of diabetes in consumers as an attenuating effect on inflammatory cells, inhibition of absorption of glucose and fat in the intestine, and increased insulin sensitivity." (PMID 32102422, 2020). "In mice, α-cells can become insulin-expressing cells after β-cell ablation, thus promoting diabetes recovery." (PMID 32477262, 2020). "In multivariate logistic regression models, high C-peptide and testosterone levels, diabetes, and hypertension were independent risk factors after adjustment for BMI, WHR, family history of cancer, high serum insulin, and estrone levels." (PMID 32913460, 2020). "Apigenin and rutin were shown to have guarded pancreatic β-cells by elevating the levels of antioxidants, antioxidant enzymes, and insulin in rat models of streptozotocin-induced diabetes." (PMID 33299532, 2020). "This is similar to type 1 diabetes mellitus in which auto-immune degeneration of the pancreatic cells results in decreased insulin levels." (PMID 32095207, 2020). "According to the World Health Organization, about 422 million people need insulin to treat diabetes and 1.6 million deaths are directly attributed to diabetes each year." (PMID 32992893, 2020). "Impaired levels of insulin occur in diabetes which results in the disability of the cells to uptake glucose from the blood." (PMID 32509880, 2020). "Individuals with a combination of reduced insulin response and insulin resistance together can be protected from frank diabetes by a maintained glucose effectiveness." (PMID 33658981, 2020). "EG members with prediabetes/diabetes improved significantly in their blood sugar level control and insulin sensitivity, together with triglycerides and HDL cholesterol levels in comparison with the CG group." (PMID 31947784, 2020).
diabetes (continued). "The AERx Insulin Diabetes Management System (iDMS) was developed in collaboration between Aradigm Corporation and Novo Nordisk." (PMID 32785196, 2020). "Type 2 diabetes mellitus (T2DM) has been associated with insulin resistance and the failure of β-cells to produce and secrete enough insulin as the disease progresses." (PMID 32218947, 2020). "Patients with a history of diabetes were managed with either oral anti-glycaemic agents or insulin alone or with a combination of oral agents and insulin." (PMID 33317506, 2020). "In a subsequent study by the same group, they used streptozotocin, a drug known to kill insulin-producing pancreatic beta cells, to induce Type 1 diabetes mellitus." (PMID 32194500, 2020). "Until recently, many children being managed for diabetes were on mixtard insulin regimen, most of them receiving them for free following donation from Life for a child foundation like in Rwanda." (PMID 32874425, 2020). "Diabetes is characterized by insulin resistance and/or insufficient secretion of insulin, hyperglycemia and hyperlipidemia, and type-2 diabetes mellitus (T2DM) accounts for over 90% of all diabetic patients." (PMID 33322303, 2020). "Originally developed to follow insulin secretion from Langerhans islets in Diabetes treatment, the ACE model allows longitudinal, non-invasive in vivo imaging of anti-islet immune responses with single-cell resolution in real time." (PMID 32696761, 2020). "It is unclear why the correlation between ucOC and insulin secretion was found only in individuals with diabetes." (PMID 32821293, 2020). "Transient insulin therapy was administered to patients N.1 and N.2 in whom a steroid-induced diabetes mellitus occurred." (PMID 33174125, 2020). "The discriminatory power of these two salivary ATR-FTIR bands area are candidates for monitoring diabetes under insulin therapy." (PMID 32182246, 2020). "Little is known about the jejunal insulin signalling pathways in insulin resistance/diabetes states and their possible regulation by insulin/leptin." (PMID 31936857, 2020). "The busy schedule in the middle/high schools made it unfeasible for the adolescents with diabetes to test glycemic levels and calculate insulin dosages on time." (PMID 32708617, 2020). "Impaired insulin action in diabetes, as well as disorders of GLUT4 vesicle trafficking in the muscle, are involved in defects in insulin-stimulated GLUT4 translocation." (PMID 33256066, 2020). "Such ROS accumulation in pancreatic β cells causes irreparable mitochondrial damage, resulting inhibition of insulin synthesis, and thus leading to diabetes progression by failing to produce enough level of insulin." (PMID 33382706, 2020). "Type 1 diabetes mellitus (DM) is a chronic illness known as insulin-dependent diabetes and characterized by irreversible, autoimmune, insulin producing islet β-cell destruction." (PMID 32215008, 2020). "This study aims to explore a cheaper alternative for producing monomeric human insulin analog to treat diabetes." (PMID 31918694, 2020). "It is well known that diabetic patients generally follow a diabetes management plan by taking their insulin regularly." (PMID 32961757, 2020). "Characterized by hyperglycemia and the insufficient secretion or action of insulin, diabetes is a metabolic disorder that amplifies inflammatory immune responses resulting in diabetes complications." (PMID 32143604, 2020). "Thus, we speculate that IRS1 p.His713Tyr variant causes a defect in binding with PI3K, resulting in a decrease in IRS1-associated PI3K activity and subsequent activation of the kinase Akt and ultimately impairs the insulin message to the cellular vector pathways, thereby causing diabetes." (PMID 32411229, 2020). "A number of preclinical and clinical investigations have shown the beneficial effect of curcumin in attenuating body weight gain, improving insulin sensitivity, and preventing diabetes development." (PMID 32781724, 2020).
diabetes (continued). "It involves a multidisciplinary work to manage the different features of this disorder such as insulin therapy (for diabetes mellitus), vasopressin (for diabetes insipidus), and hearing aids or cochlear implants (for hearing loss)." (PMID 32419160, 2020). "The conventional way to treat diabetes is to inject insulin using subcutaneous administration, but the development of an effective orally administered insulin formulation would be preferred." (PMID 32887466, 2020). "The hypoglycemic effect of Myrcia bella leaf extract in mice with STZ-induced diabetes can increase the expression of the insulin-signaling pathway involving PI3K/Akt proteins." (PMID 32425738, 2020). "Kaempferol, a flavanol found in honey, was reported to have prevented pancreatic β cell dysfunction in middle-aged obese mice with diabetes, and enhanced peripheral insulin sensitivity." (PMID 33299532, 2020). "Total direct diabetes-specific costs ranged between €774.66 in the year prior to insulin initiation use for patients discontinuing this treatment within 3 months and €2204.41 for patients in the year after insulin initiation." (PMID 33198734, 2020). "In pre-diabetes, individuals present with only slightly elevated blood glucose levels as the pancreas seeks to compensate with increased insulin secretion for many years until type 2 diabetes mellitus is diagnosed." (PMID 33553233, 2020). "Prior to this study, a diabetic mouse model fed with Enzogenol® was reported to improve diabetes-related biomarkers with a reduction in HbA1c, insulin, and glucagon levels, and an elevation of hepatic AMP-activated protein kinase (AMPK) activity." (PMID 32075228, 2020). "The pathogenesis of diabetes includes insulin resistance and insulin secretion disorders of islet beta cells." (PMID 33195466, 2020). "In this review, we focus on the most recent findings on insulin synthesis, highlighting their relevance in diabetes." (PMID 32894308, 2020). "Nearly everyone with T1D received an insulin prescription at any time (59 of 60 people, 98.3% sensitivity), and almost all received it within 90 days of diabetes diagnosis (58 of 59 people, 96.7% sensitivity)." (PMID 32093635, 2020). "Although the mechanism of diabetes-induced podocyte apoptosis is still unclear, previous reports clearly showed that inhibition of insulin and VEGF actions by SHP-1 plays a key role in development of podocyte apoptosis." (PMID 32238837, 2020). "Compared with subcutaneous fat, abdominal fat is more difficult to the antilipolytic function of insulin, for which, the abdominal fat plays an essential role in insulin resistance and diabetes." (PMID 32090477, 2020). "In the treatment of diabetes mellitus, the goal is to achieve blood glucose levels closer to the normal range by subcutaneous injections of insulin preparations." (PMID 35515176, 2020). "As a mechanism for the onset of diseases such as obesity, insulin sensitivity, and diabetes, advanced glycation end products (AGEs) are getting attention." (PMID 32684824, 2020). "We did not assess the degree of glucose control, but the number of cases of diabetes treated with insulin was small." (PMID 32599847, 2020). "In relatively short follow-up studies (up to 15 years), high glucose levels in an OGTT, age, BMI, insulin treatment during pregnancy and a single autoantibody positivity have been predictive factors of later onset of diabetes." (PMID 32725280, 2020). "2‐II‐1 received treatment of insulin for diabetes, levothyroxine for hypothyroidism, and polyene phosphatidyl choline for hepatic protection." (PMID 33016646, 2020). "About the medications used for treatment of diabetes, consumers raised more questions about insulin, metformin, gliclazide, and xiaokepill." (PMID 32576159, 2020). "Thirdly, we have found that early de-prescription of diabetes medications is essential, in particular insulin, sulphonylureas, and sodium-glucose cotransporter (SGLT2) inhibitors." (PMID 32276484, 2020).
diabetes (continued). "In diabetes, recovery of insulin effects (pharmacological use of insulin or insulin-sensitizers use) can prevent the occurrence of microvascular alterations." (PMID 31963760, 2020). "The studies have been described that HDAC and HAT regulation are related to signaling of insulin, apoptosis and inflammation which has effect on the both type of diabetes." (PMID 32815547, 2020). "A non-parametric Kruskal Wallis H test was performed to compare the effect of educational status, duration of insulin therapy, and duration of diabetes on patients’ level of knowledge for insulin storage and handling techniques." (PMID 33046046, 2020). "Diabetes, particularly Type 2, results from insulin resistance and failure of beta-cell function, with the former preceding the latter." (PMID 32267855, 2020). "The chapters on diabetes etiology and celebrities with diabetes were particularly engaging for children, whereas the chapters that demonstrated diabetes management and care (eg, insulin injection) were of interest to parents." (PMID 32356773, 2020). "Education (P < 0.001), occupation (P < 0.001), duration of insulin therapy (P = 0.001), duration of diabetes (P = 0.036) and patients’ knowledge level (P < 0.001) were found to have a significant effects on the patients’ practice levels." (PMID 33046046, 2020). "Understanding the biology underlying the mechanisms and pathways regulating pancreatic β cell development is necessary to understand the pathology of diabetes mellitus (DM), which is characterized by the progressive reduction in insulin-producing β cell mass." (PMID 33121533, 2020). "The percentages of patients with diabetes and insulin treatment were lower in those who received PAI with dexamethasone than in those who received PAI alone (16.6% vs 47.3%, P < 0.001 and 0.5% vs 10.9%, P < 0.001, respectively)." (PMID 32822007, 2020). "A decrease in β-cell mass, which occurs during the progression of Type 2 diabetes mellitus, contributes to impaired insulin secretion." (PMID 32375753, 2020). "Diabetes mellitus (DM) involves a group of chronic metabolic disorders with existing chronic hyperglycemia, defects of insulin action, secretion or both; with altered fat, protein and carbohydrate metabolism." (PMID 33031385, 2020). "Diabetes mellitus (DM) is a chronic disease, a condition caused either by insufficient insulin secretion or insulin resistance characterized by hyperglycemia, and is widely prevalent worldwide and usually accompanied by impaired glucose tolerance (IGT), hypertension and hyperlipidemia." (PMID 32521609, 2020). "In MafA knockout mice, insulin biosynthesis and secretion are reduced, leading to diabetes mellitus, indicating the importance of MafA in β-cells." (PMID 33322512, 2020). "Type 2 diabetes mellitus develops when the pancreatic β cells become “exhausted” and cannot secrete adequate amounts of insulin to preserve normoglycemia in an increasing IR environment." (PMID 32849275, 2020). "Diabetes mellitus is classified into two types: insulin-dependent (that results from destruction of pancreatic β cells of Langerhans) and noninsulin-dependent (that results from defects in insulin action and/or secretion)." (PMID 32104544, 2020). "The beneficial effects of thiazolidinediones in diabetes treatment are to improve the sensitivity of insulin, decrease insulin resistance and also decrease cardiovascular risks." (PMID 32872226, 2020). "Frequent and regular blood glucose testing is crucial for diabetics, who need regular insulin injections to maintain their blood glucose balance." (PMID 33291519, 2020). "Within the diabetes group, 17% reported insulin restriction at least once per week in order to control weight." (PMID 32128205, 2020). "Data were reviewed weekly by a member of the diabetes care team and youth and/or caregivers were contacted for insulin dose adjustments and/or education." (PMID 32733375, 2020).
diabetes (continued). "Increased hepatic glucose production occurs early during diabetes, although the increase is more obvious after the onset of insulin secretory abnormalities and insulin resistance in skeletal muscle." (PMID 32927754, 2020). "Expanding the mass of pancreatic insulin-producing beta cells through re-activation of beta cell replication has been proposed as a therapy to prevent or delay the appearance of diabetes." (PMID 33239617, 2020). "Human embryonic stem cells represent a potentially unlimited source of insulin-producing cells for diabetes therapy." (PMID 32345350, 2020). "Incorporating the opportunities that bioelectronic medicine offers for diabetes will undoubtedly enable improved computation of the insulin doses, increased autonomy, and personalized glucose control." (PMID 32467827, 2020). "The insulin pathway in the osteoblast plays an essential role in miR-26a-mediated protection in diabetes and bone health, as a compromise of insulin signaling in osteoblasts abolished these effects." (PMID 32278305, 2020). "Disturbances in adipocytokine profiles can contribute to peripheral insulin resistance and impairment of insulin production, which are 2 primary pathophysiological mechanisms involved in type 2 diabetes mellitus (T2DM)." (PMID 32028423, 2020). "The roles of sirtuins in both carbohydrate and lipid metabolism is still controversial, despite many studies based on various experimental models of diabetes and insulin resistance demonstrating improved glucose tolerance, insulin secretion and sensitivity." (PMID 32927638, 2020). "The results are confirmed by the Ins1-Cre β-cell cilia knockout (βCKO) mouse, which showed decreased insulin secretion, glucose intolerance, and diabetes development." (PMID 33139642, 2020). "Following a high fiber, prebiotic, dietary supplement, there was a subsequent reduction in the use of medicine for diabetes (insulin) and hypertension treatment (ACE inhibitors), and also a lowering of blood pressure." (PMID 33072796, 2020). "A patient with type 1 diabetes mellitus self-administered 4050 units of high-concentration (300 units/mL) insulin glargine, in addition to coingestants." (PMID 32342025, 2020). "One of the beneficial strategies postulated as a possible therapy for diabetes is to increase functional insulin-producing β-cells via endogenous pancreatic β-cell regeneration." (PMID 33553143, 2020). "Insulin and insulin analogs used in the treatment of diabetes supported the growth of the breast tumor through the activation of mitogenic and angiogenic signaling mechanisms." (PMID 32883003, 2020). "The expression of this enzyme is significantly altered by insulin and therefore decreases in diabetes." (PMID 30927246, 2020). "Lower intakes of folate and potassium among individuals with diabetes, particularly among women, raises the issue of improving intakes in this population in view that these micronutrients play a significant role in insulin synthesis and sensitivity." (PMID 33198057, 2020). "This property makes of D-Pinitol a dietary supplement of potential utility in a pro-diabetes scenario (i.e., obesity, aging, etc.), in which the pancreas becomes exhausted due to an overproduction of an inefficient insulin." (PMID 32650579, 2020). "Dysregulation of proinflammatory and anti-inflammatory cytokines not only impairs insulin secretion by pancreatic β-cells but also results in systemic complications in late diabetes." (PMID 33424779, 2020). "Rap1 signaling pathway: some studies indicated that activated Rap1A promoted glucose-stimulated insulin secretion, islet cell hypertrophy, and islet cell proliferation, and it can be a unique target for the treatment of beta-cell dysfunction in diabetes." (PMID 33292335, 2020). "More important, except painlessness, adjusting insulin release according to the concentration of blood glucose is so important that can decrease the multiple side effects from diabetes." (PMID 32664978, 2020).